ISG15 (ISG15 ubiquitin like modifier)
Diseases named in the same sentence as ISG15 in open-access papers (continued):
Sharing a sentence is not in itself a finding about the gene and the disease.
Hepatic steatosis (1 paper, 2025). Steatosis is a term used to denote lipid accumulation within hepatocytes. "In mouse models and clinical HCC samples, upregulation of ISG15 is associated with hepatic steatosis." (PMID 40126377, 2025). "Furthermore, similar to ISG15, HMGA1 was also upregulated in clinic NAFLD samples compared with healthy liver tissues (GEO GSE130970), suggesting a potential association between HMGA1 and fatty liver." (PMID 40126377, 2025).
hepatitis E virus infection (1 paper, 2020). Acute inflammation of the liver in humans; caused by hepatitis E virus, a non-enveloped single-stranded rna virus. "Additionally, ISG15 levels are significantly elevated in patients with chronic hepatitis C virus and hepatitis E virus infection." (PMID 32575635, 2020).
Hyperglycemia (1 paper, 2023). An increased concentration of glucose in the blood. "Our combined method of ATAC and RNA sequencing revealed Csf2rb, Btla, and Isg15 as the key candidate genes associated with hyperglycemia, azotemia, and albuminuria." (PMID 38022502, 2023). "In the current study, the univariate analysis including all mice from three groups demonstrated that Isg15 expression levels were positively correlated to hyperglycemia and UACR, suggesting its deleterious role in DKD." (PMID 38022502, 2023).
hyperthyroidism (1 paper, 2024). Overactivity of the thyroid gland resulting in overproduction of thyroid hormone and increased metabolic rate. "Our study indicates that ISG15 can serve as a diagnostic biomarker for hyperthyroidism, ZNF683 can be considered as one of the diagnostic biomarkers for hypothyroidism, and elevated expression of IGHG3 suggests abnormal thyroid function in patients." (PMID 39872521, 2024). "Our research highlights the specific high expression of ISG15 in hyperthyroidism patients and its correlation with thyroid function, suggesting that ISG15 could serve as a diagnostic biomarker for hyperthyroidism." (PMID 39872521, 2024). "Subsequently, we regulated a correlation analysis among representative of ISG15 and clinical blood parameters as well as fundamental characteristics in sicks with hyperthyroidism." (PMID 39872521, 2024). "Key signaling molecules were identified: ISG15 for hyperthyroidism, ZNF683 for hypothyroidism, and IGHG3 common to both conditions." (PMID 39872521, 2024). "In this research, we employed a combined decomposition of gene transcriptomics and proteomics to recognize ISG15 as a differential gene unique to patients with primary hyperthyroidism compared to healthy individuals." (PMID 39872521, 2024). "We observed an enhancement expression of ISG15 in the serum of hyperthyroidism patients, indicating a significant correlation between ISG15 and GD." (PMID 39872521, 2024). "Using clinical baseline data collected from participants and ELISA results for IGHG3, ISG15, and ZNF683, we randomly divided the samples into training and testing groups to construct prediction models for patients with AITD hyperthyroidism and hypothyroidism." (PMID 39872521, 2024). "The expression levels of IGHG3, ISG15, and ZNF683 were analyzed in relation to clinical examination data from patients with hyperthyroidism, hypothyroidism, and healthy individuals." (PMID 39872521, 2024).
idiopathic basal ganglia calcification (1 paper, 2016). "A less severe phenotype has been described in patients presenting with idiopathic basal ganglia calcification (IBGC), seizures and autoantibodies, and harboring mutations in the ISG15 gene (IMD38, OMIM #616126)." (PMID 27260006, 2016).
infectious mononucleosis (1 paper, 2021). A condition characterized by an increase in mononuclear white blood cells and swollen lymph nodes, which is usually caused by infection with the Epstein-Barr virus. "Moreover, HLA-DMB, GADD45A, and ISG15 are reported to be involved in Epstein–Barr virus infection, one of the most common human viruses in the world, causing infectious mononucleosis and other illnesses." (PMID 34442377, 2021).
inflammatory skin disease (1 paper, 2024). Inflammatory skin disorders covers a broad category that includes many conditions ranging in severity, from mild itching to grave medical health complications These disorders are common in people of all ages and races. "Detecting ISG15 in skin lesions may help physicians and patients to identify DM and distinguish it from other similar-looking inflammatory skin diseases." (PMID 39559355, 2024).
ischemia (1 paper, 2023). A hypoperfusion of the BLOOD through an organ or tissue caused by a PATHOLOGIC CONSTRICTION or obstruction of its BLOOD VESSELS, or an absence of BLOOD CIRCULATION. "Finally, having observed the preservation of cardiac function in Isg15–/– mice after TAC and in mouse hearts following ex vivo ischemia/reperfusion, we explored possible mechanisms underlying the cardioprotective effect of ISG15 absence." (PMID 37115698, 2023).
ischemia reperfusion injury (1 paper, 2024). Adverse functional, metabolic, or structural changes in ischemic tissues resulting from the restoration of blood flow to the tissue (reperfusion), including swelling; hemorrhage; necrosis; and damage from free radicals. "The interferon-stimulated gene 15 (ISG15) level was upregulated in the kidneys of mice injured by ischemia-reperfusion injury (IRI), cisplatin, or unilateral ureteral obstruction (UUO), however, its role in AKI development and subsequent AKI-to-CKD transition remains unknown." (PMID 39113797, 2024).
kidney cancer (1 paper, 2022). Primary or metastatic malignant neoplasm involving the kidney. "In kidney cancer, ISG15 has been investigated as a novel protein adjuvant in vaccines." (PMID 36189312, 2022).
laryngeal carcinoma (1 paper, 2025). Carcinoma that arises from the laryngeal epithelium. "ISG15, ITGB1, PXN, SLC2A1 and ICAM1 are expected to become potential therapeutic targets for HPV-positive laryngeal cancer." (PMID 40821990, 2025). "Key genes like CDC42, PXN, ITGB1, PGK1, SLC2A1, ISG15 and ICAM1, affected by HPV, display distinct functional alterations and complex correlations in laryngeal cancer progression." (PMID 40821990, 2025). "PXN, ITGB1, ISG15, SLC2A1 and ICAM1 are regarded as potential therapeutic targets for HPV-positive laryngeal cancer." (PMID 40821990, 2025).
leukopenia (1 paper, 2019). "However, the up-regulation of the ISG15 pathway in unvaccinated pigs after CSFV Brescia challenge is most likely associated with the failed attempt of the immune system to induce an antiviral response after infection, contributing to clinical disease including leukopenia." (PMID 31396205, 2019).
liver cirrhosis (1 paper, 2020). "Furthermore, ISG-15 expression in PBMCs of patients with liver cirrhosis correlated significantly with IL-7-serum levels, suggesting an in vivo correlation between the activity of the IFN-system and IL-7 production." (PMID 33584648, 2020).
Miscarriage (1 paper, 2025). A pregnancy that ends at a stage in which the fetus is incapable of surviving on its own, defined as the spontaneous loss of a fetus before the 22th week of pregnancy. "We selected ISG15, a hub gene that showed similar trends in qPCR outcomes in the mouse model of miscarriage and in patients with RM, for further validation at the protein level." (PMID 39508749, 2025).
motor neuron disease (1 paper, 2021). "ISG15 is in the type-I-interferon (IFN) signaling cascade and is increased after cell stress, in neuronal injury and motor neuron disease (ALS) in humans and mice." (PMID 33927318, 2021).
Moyamoya disease (1 paper, 2024). Moyamoya disease (MMD) is a rare intracranial arteriopathy involving progressive stenosis of the cerebral vasculature located at the base of the brain causing transient ischemic attacks or strokes. "Next, the expression levels of five key genes were found to correlate with the expression levels of several moyamoya disease-related genes, with H19 positively correlating with ADARB2 (Pearson r = 0.628) and STK3 negatively correlating with ISG15 (Pearson r = − 0.556)." (PMID 38704490, 2024).
nonischemic cardiomyopathy (1 paper, 2023). Forms of cardiomyopathy that are not related to known coronary artery disease. "Next, we queried whether ISG15 induction and protein ISGylation also occur in human cardiomyocytes and whether ISG15 upregulation also occurs in human nonischemic cardiomyopathy (NICM)." (PMID 37115698, 2023).
osteoarthritis (1 paper, 2025). A noninflammatory degenerative joint disease occurring chiefly in older persons, characterized by degeneration of the articular cartilage, hypertrophy of bone at the margins and changes in the synovial membrane. "Osteoarthritis: PARP12↑ → binds ISG15 → ↑MFN1/2 isoprenylation → inhibits PINK1/Parkin‐mediated mitophagy → promotes cartilage degradation." (PMID 40904702, 2025).
prostate tumors (1 paper, 2013). "This analysis revealed a prominent inverse correlation between uc.106 + A expression and the expression of many interferon pathway genes such as IRF7, ISG15, ISG20, OAS1-3, and PTPN22 in prostate tumors." (PMID 23409773, 2013).
psoriasis vulgaris (1 paper, 2022). Plaque psoriasis is the most common presentation of psoriasis. "In summary, we demonstrated that the presence of IL36G may mediate the keratinocyte expression of AVPs such as MX1, ISG15, IFI27, and IFI44L in psoriasis vulgaris." (PMID 36172384, 2022).
rectal cancer (1 paper, 2026). A primary or metastatic malignant neoplasm that affects the rectum. "Here, we showed that HFRT increases ISG15+MHC-I+ neutrophil infiltration, which exhibits antigen-presenting capabilities and is crucial for successful neoadjuvant therapy in rectal cancer." (PMID 41824789, 2026).
reovirus infection (1 paper, 2015). "Further, reovirus infection up-regulated the transcription of ISGs, namely IFITM1, ISG15 and Viperin, and blockage of the PI3K/Akt pathway in reovirus infection inhibited the expression of IFITM1, ISG15 and Viperin." (PMID 26388843, 2015).
skin tumors (1 paper, 2025). "Consistently, we observed inflammatory genes, including Ifng, Stat1, Ifit2, Ifit3, Isg15, and Bst2, being highly expressed in the T cell cluster in skin tumors." (PMID 40282557, 2025).
streptococcal pneumonia (1 paper, 2021). A febrile disease caused by streptococcus pneumoniae. "One patient (P37) was identified with ISG15 defect, born of a third-degree consanguineous marriage had presented at 3 months of age with BCG-osis, he also had Bocavirus infection and recurrent Streptococcal pneumonia." (PMID 33732252, 2021).
Ta (1 paper, 2006). "Comparison of ISG15 gene expression in nine normal urothelium samples and 45 Ta tumours revealed a 2.7-fold increase in ISG15 transcript expression in Ta tumours (P=1.31E−05)." (PMID 16641915, 2006). "In agreement with the first microarray study, the ISG15 transcript was increased in Ta tumours (1.4-fold, P=5.00E−05), in T1 tumours (1.7-fold, P=4.14E-08), and to the greatest extent in T2–T4 tumours (2.0-fold, P=4.12E-13) compared to normal bladder." (PMID 16641915, 2006).
thyroid tumor (1 paper, 2022). A benign or malignant neoplasm affecting the thyroid gland. "Plastin-2, playing a crucial role in the development of thyroid tumors, and ISG15 (interferon-stimulated gene 15 or interferon-induced 17 kDa protein precursor) are of great interest." (PMID 35328492, 2022).
uveal melanoma (1 paper, 2025). A melanoma derived from melanocytes of the uveal tract. "Based on our results from the GEPIA2 database, ISG15 expression levels notably correlated with the prognosis of KIRC, LGG, SKCM, UVM (uveal melanoma), PRAD, and UCEC." (PMID 40208307, 2025).
wart (1 paper, 2021). "In immunohistochemical staining, the expressions of ISGs such as ISG15, OAS1, and MxA commonly declined in HPV-2 wart samples." (PMID 33670861, 2021).
Werner syndrome (1 paper, 2018). "Similar to senescent NHDFs, fibroblasts from a patient with Werner syndrome also showed higher expression levels of the ISGs, IFIT3, OASL, ISG15, Mx2, and IFIT27, even at earlier passages." (PMID 30455980, 2018).
whipworm infection (1 paper, 2022). "Further research is needed to understand the molecular mechanisms leading to Isg15 expression by IECs and the role of this alarmin in host responses to whipworm infection." (PMID 35365634, 2022). "We validated the expansion of Isg15-expressing enterocytes in response to whipworm infection using mRNA ISH by HCR on caecal tissues from uninfected and T. muris-infected mice after 24 and 72 h p.i.." (PMID 35365634, 2022).
Zinc deficiency (1 paper, 2023). A deficiency of the essential metal Zinc; an essential cofactor for many enzymes. "This study presents a remarkable case series of a consanguineous family with a homozygous variant in the ISG15 gene, leading to a complex interplay of intriguing dermatological manifestations and concurrent zinc deficiency." (PMID 38234945, 2023).
infection (470 papers, 2006 to 2026). The state of being infected such as from the introduction of a foreign agent such as serum, vaccine, antigenic substance or organism. "Interferon-stimulated gene 15 (ISG15) is one of the strongest interferon-stimulated genes following pathogenic infection, and ISGylation plays a key role in our innate immune system." (PMID 40631552, 2025). "The INF-α downstream targets Isg15 and Mx1, implicated in host response to infection and inflammation, were also upregulated, particularly after 24 h of IMQ exposure." (PMID 40574053, 2025). "Given the importance of ISGylation during infection, many viruses encode proteases that cleave ISG15 from viral and host proteins to hijack its antiviral function." (PMID 40631552, 2025). "Of note, the infection caused significant upregulation in mRNA expression level of interferon-stimulated genes (Isg15, Mx1, Mx2, Irf3, and Irf7) and pro-inflammatory cytokines (Tnf-α, Cxcl-1, and Il-6 genes)." (PMID 37929187, 2023). "Infection with A. actinomycetemcomitans caused a significant upregulation in the expression levels of Isg15, Mx1, Mx2, Irf3, Irf7, Tlr-2, Tnf-α, Cxcl-1, and Il-6 genes." (PMID 37929187, 2023). "Upon infection with all variants, the evaluated ISGs, Cxcl10, Isg15, and Mx-1, were upregulated and the expression levels for B.1.1 were the highest, followed by those for BA.2 and BA.5 in the lung hilum area." (PMID 37488344, 2023). "ISG15 is robustly induced by IFNs, interleukin 1 beta (IL-1β), pathogenic infection, lipopolysaccharides (LPS), retinoic acid (RA), hypoxia, experimental stroke traumatic brain injury, or DNA-damaging stresses." (PMID 36319753, 2022). "One report shows that mice that are deficient in ISG15 have an increased susceptibility to infection with several viruses including HSV-1." (PMID 36423126, 2022). "Here, we demonstrate that IFN-I primed fibroblasts derived from ISG15-deficient individuals are more resistant to infection with single-cycle HIV-1 compared to healthy control fibroblasts." (PMID 35333911, 2022). "ISG15 encodes a ubiquitin-like protein that interacts with viral proteins during infection, resulting in their loss of function." (PMID 36298734, 2022). "Despite a slight increase of IFN-β and -λ induction in SARS-CoV-2 Alpha variant induction compared to D614G lineage in single infection, IFNs and ISG15 inductions were comparable between the two variants at day 5 in the context of dual infection." (PMID 34931581, 2022). "Infection with HCMV bearing a mutation in the UL26 gene demonstrated increased ISG15 expression as well as ISGylated proteins." (PMID 34299120, 2021). "There were subtle differences in plaque phenotype; for instance, infection of ISG15-deficient cells, particularly with HPIV2 but also evident following PIV5 infection, resulted in plaques with poorer defined edges (hazy plaques)." (PMID 32423918, 2020). "In contrast to HRSV, ISG15-deficient cells were shown to be resistant to infection by paramyxoviruses such as SeV, NiV and PIV-5, suggesting a pro-viral role for ISG15 to facilitate efficient cellular infection." (PMID 33276587, 2020). "Here, we address this obstacle by defining the quantitative, proteome-wide ubiquitylome in Isg15-deficient animals prior to and following infection." (PMID 31772204, 2019). "ISG15 is established as critical protein modifier during anti-viral responses with Isg15−/− mice being more susceptible to infection." (PMID 31073301, 2019). "Ubiquitin sites induced by infection (present in Isg15-deficient animals) had a 75% overlap with published ubiquitin sites." (PMID 31772204, 2019). "ISG15 encodes a 15 kDa protein which is strongly induced in immune cells after type I IFN treatment or pathogen infection and has a significant sequence homology to ubiquitin." (PMID 30469497, 2018). "Many studies have also implicated UBE2L6 and ISG15 as critical components of the innate immune response to pathogen infection." (PMID 28186990, 2017).